AWAT1 (acyl-CoA wax alcohol acyltransferase 1)
Description:
Acyltransferase that catalyzes the formation of ester bonds between fatty alcohols and fatty acyl-CoAs to form wax monoesters. Shows a strong preference for decyl alcohol (C10), with less activity towards C16 and C18 alcohols. Shows a strong preference for saturated acyl-CoAs.
Synonyms: DGA2; DGAT2L3
Tractability: Antibody: UniProt predicts a signal peptide or a membrane-spanning region.
Target class: Enzyme; Transferase
Gene: Protein-coding gene on chromosome X (70,234,655 to 70,240,659, forward strand). Ensembl gene ENSG00000204195.
Subcellular location: Endoplasmic reticulum membrane
Pathways (Reactome):
Metabolism: Arachidonate metabolism; Wax biosynthesis
Gene Ontology:
Molecular function: long-chain-alcohol O-fatty-acyltransferase activity; acyltransferase activity, transferring groups other than amino-acyl groups; diacylglycerol O-acyltransferase activity
Biological process: arachidonate metabolic process; wax biosynthetic process
Cellular component: endoplasmic reticulum membrane
Homologues: Orthologues: chimpanzee AWAT1 (99% identical), macaque AWAT1 (97% identical), dog AWAT1 (88% identical), guinea pig AWAT1 (88% identical), rat Awat1 (82% identical), mouse Awat1 (82% identical), rabbit AWAT1 (75% identical), Caenorhabditis elegans Y53G8B.2 (39% identical), Caenorhabditis elegans K07B1.4 (38% identical), Caenorhabditis elegans dgat-2 (37% identical), Caenorhabditis elegans dgtr-1 (36% identical), Drosophila melanogaster CG1941 (36% identical), and 2 more. Paralogues in human: DGAT2L6 (52% identical), AWAT2 (51% identical), DGAT2 (51% identical), MOGAT3 (45% identical), MOGAT2 (43% identical), MOGAT1 (42% identical).
Diseases named in the same sentence as AWAT1 in open-access papers:
AWAT1 is named in the same sentence as 11 diseases in open-access papers, as found by Europe PMC text mining. Sharing a sentence is not in itself a finding about the gene and the disease. The quoted sentences say what the papers report.
dry eye (2 papers, 2021 to 2022). "Awat2 knockout mice and Awat1 and Awat2 double knockout mice expressed severe dry eye with MGD, whereas Awat1 knockout mice had only mild dry eye." (PMID 35685417, 2022). "Awat2 KO and DKO mice exhibited severe dry eye with meibomian gland dysfunction, whereas Awat1 KO mice had mild dry eye." (PMID 34113821, 2021). "In the present study, we have elucidated the detailed composition of several ester-bond-containing meibum lipids in mice and gained insights into their roles in dry eye prevention and the contributions of Awat1 and Awat2 to their production." (PMID 34113821, 2021). "Here, we created single and double knockout (KO and DKO, respectively) mice for the two acyl-CoA wax alcohol acyltransferases (Awat1 and Awat2) and investigated their dry eye phenotypes and meibum lipid composition." (PMID 34113821, 2021). "The fact that the dry eye phenotype of the Tg Cyp4f39 KO mice was more severe than that of the Awat1 KO mice may be the result of the additional reduction of type 2ω WdiEs and Chl-OAHFAs." (PMID 34113821, 2021). "The dry eye phenotypes, in descending order of severity, in all four mouse lines are as follows: Awat2 KO mice ≈ DKO mice > Tg Cyp4f39 KO mice > Awat1 KO mice." (PMID 34113821, 2021). "In the present study, we generated Awat1 KO, Awat2 KO, and Awat1 Awat2 double KO (DKO) mice and used them to examine the contribution of Awat1 and Awat2 to the production of meibum lipids, as well as their roles in dry eye prevention." (PMID 34113821, 2021).
AWAT1 also shares sentences with these, for which no sentence is quoted: Hepatic steatosis (7 papers); steatosis (3); Insulin resistance (2); breast carcinoma (1); cancer (1); Dyslipidaemia (1); dyslipidemia (1); peripheral neuropathy (1); psoriasis (1); tumor (1).